FABP4 (fatty acid binding protein 4)
Diseases named in the same sentence as FABP4 in open-access papers (continued):
Sharing a sentence is not in itself a finding about the gene and the disease.
periodontitis (4 papers, 2022 to 2025). An acute or chronic inflammatory process that affects the tissues that surround and support the teeth. "A better understanding of the FABP4 will improve preventive, diagnostic, therapeutic and reparative strategies for periodontitis and related systemic disease." (PMID 40002815, 2025). "We suggest that molecules that inhibit FABP4, which is associated with periodontitis and systemic inflammation, may be helpful in the treatment of periodontitis." (PMID 40002815, 2025). "As the severity of periodontitis increased, serum FABP4 and P. gingivalis antibody titer level increased." (PMID 40002815, 2025). "Further research should explore the role of FABP4 in patients with periodontitis and systemic diseases to strengthen its clinical relevance." (PMID 40002815, 2025). "Within the limitation of our study, the host serum FABP4 levels increased with increasing periodontitis severity." (PMID 40002815, 2025). "Our study results showed that as periodontitis became more severe, serum FABP4 levels, is involved in the regulation of low-grade systemic and chronic inflammation, increased." (PMID 40002815, 2025). "Our study aimed to investigate the relationship between FABP4 and P. gingivalis antibody titer according to the stage of periodontitis." (PMID 40002815, 2025). "Therefore, we aim to explore the significant role of FABP4 in the severity of periodontitis and discuss its usefulness as a biomarker linking periodontitis and systemic diseases." (PMID 40002815, 2025). "Therefore, we consider the potential use of FABP4 as a biomarker for diagnosis and predicting stage of periodontitis." (PMID 40002815, 2025). "There are few studies suggesting the use of FABP4 as a biomarker related to periodontitis." (PMID 40002815, 2025). "We propose FABP4 as a potential biomarker for the evaluation of periodontitis." (PMID 40002815, 2025). "These pieces of evidence clinically indicate that periodontitis is related to serum FABP4." (PMID 40002815, 2025). "Moreover, a notable positive association was observed between serum Pg antibody and FABP4 level in clinical periodontitis patients, suggesting that Pg can promote AS and other systemic diseases by affecting FABP4." (PMID 37629042, 2023). "Background/Objectives: This study aims to investigate the relationship between serum fatty acid-binding protein 4 (FABP4) levels and the severity of periodontitis in systemically healthy individuals." (PMID 40002815, 2025). "A total of 7 genes (CD19, CXCR4, FABP4, FOS, IGHD, IL2RG, and PPBP) were upregulated in periodontitis samples." (PMID 39917706, 2024). "In this study, seven genes (CD19, CXCR4, FABP4, FOS, IGHD, IL2RG, and PPBP) were significantly up-regulated in periodontitis samples." (PMID 39917706, 2024). "Non-surgical periodontal treatment led to decrease in serum FABP4 level across all stages of periodontitis." (PMID 40002815, 2025). "In this study, we measured FABP4 levels in periodontitis patients without systemic diseases to excluding various confounding factors of systemic diseases." (PMID 40002815, 2025). "After non-surgical periodontal treatment, FABP4 levels significantly decreased across all stages of periodontitis." (PMID 40002815, 2025). "Multiple linear regression showed that FABP4 levels increased significantly with the progression of periodontitis, independent of age and sex." (PMID 40002815, 2025). "The previous study examined whether the treatment of periodontitis affects the level of FABP4 within the limitation of small sample size and irrespective of the severity of periodontitis." (PMID 40002815, 2025). "Additionally, the study examines whether non-surgical periodontal treatment can reduce FABP4 levels, establishing its potential as a biomarker linking periodontitis to systemic diseases." (PMID 40002815, 2025).
periodontitis (continued). "The purpose of this study is to investigate the levels of serum FABP4 in healthy individuals without systemic disease, based on the severity of periodontitis, and to determine whether non-surgical periodontal treatment can induce changes in the levels of serum FABP4." (PMID 40002815, 2025).
prostate tumor (4 papers, 2016 to 2025). "The progression of prostate tumors in FABP4−/− TRAMP and TRAMP mice fed with different diets was compared." (PMID 41226657, 2025). "The researchers also treated metastatic prostate tumor cells with adipocyte-conditioned media and found that the expression of FABP4, IL-1β, and hemeoxygenase-1 (HMOX1) was upregulated." (PMID 36060264, 2022). "Based on these findings, the effects of FABP4 on the proliferation of metastatic prostate tumor cells were further investigated." (PMID 36060264, 2022). "In addition, the mRNA expression levels of MMP9 in the mouse prostate tumor (20, 24, and 30 weeks of age) were significantly lower in FABP4−/− TRAMP-HF than in TRAMP-HF mice." (PMID 41226657, 2025). "Furthermore, oral administration of BMS309403—a chemical inhibitor of FABP4—inhibited prostate tumor progression by modulating cytokine secretion and periprostatic adipocyte infiltration." (PMID 41226657, 2025). "Moreover, the mRNA expression levels of MMP9 in the mouse prostate tumor were significantly lower in the FABP4−/− TRAMP-HF group than in the TRAMP-HF group." (PMID 41226657, 2025). "We chose to inhibit FABP4 based on our previous studies demonstrating upregulation of this lipid transporter in prostate tumor cells exposed to marrow adipocytes, and the apparent efficacy of BMS309403 in inhibiting prostate tumor cell invasion in the 2D Boyden chamber assay." (PMID 27458427, 2016). "Next, we conducted a comprehensive metabolome analysis using prostate tumor samples from 24-week-old mice in the TRAMP-HF and FABP4−/− TRAMP-HF groups (three mice per group)." (PMID 41226657, 2025). "Among these genes, PTEN is an important tumor suppressor gene predominantly involved in human prostate tumors, whereas HMGCS1, HMGCR, SCD1, FABP4, and SCD1are critical enzymes in the pathways of lipid synthesis as well cholesterol and steroid synthesis." (PMID 32180899, 2020). "Consistent with the microarray data, we found a higher expression of HMGCS1 (3.5-fold), HMGCR (2.5-fold), SCD1 (2.5-fold), AGPS (1.9-fold), FABP4 (2.5-fold), DPT (2.2- fold), and PTEN (1.56-fold decline) in prostate tumors of LPB-Tag genotype when compared with the prostates of other genotypes." (PMID 32180899, 2020).
psoriasis (4 papers, 2017 to 2022). An autoimmune condition characterized by red, well-delineated plaques with silvery scales that are usually on the extensor surfaces and scalp. "FABP4 has been recently linked with increased cardiovascular morbidity and mortality, which is also observed in psoriasis." (PMID 30993401, 2019). "Serum FABP4 levels were significantly increased in patients with psoriasis, indicating that this protein may be a marker of psoriasis and an independent predictor of the risk of comorbidities or complications in psoriatic patients." (PMID 27864793, 2017). "A second objective of the study was to assess whether FABP3 and FABP4 could be useful for predicting the risk of cardiovascular disorders or metabolic diseases in patients with psoriasis." (PMID 27864793, 2017). "From the remaining FABPs only heart—(H-FABP, FABP3) and adipocyte fatty acid-binding protein (A-FABP, FABP4) were evaluated in patients with psoriasis in the research conducted by us." (PMID 30993401, 2019). "FABP4 has been linked to angiogenesis and vascular endothelial growth factor (VEGF), which are also highly disturbed in psoriasis." (PMID 27864793, 2017). "FABP4 levels based on psoriasis activity were significantly higher in the group with PASI <10 (p = 0.002) compared to the controls." (PMID 27864793, 2017). "Another possible role of FABP4 in psoriasis is evident in the influence on MS, which is strongly associated with psoriasis." (PMID 27864793, 2017). "These promising data enable us to draw conclusions regarding the potential use of drugs reducing FABP4 levels also for protecting patients with psoriasis from cardiovascular or metabolic disorders." (PMID 27864793, 2017). "In patients with mild psoriasis, FABP4 levels were significantly higher than those in controls before treatment (p = 0.002), but the differences did not remain significant after therapy (p = 0.09)." (PMID 27864793, 2017). "We can speculate that FABP4 may be a link between psoriasis and its metabolic comorbidities, especially because we found significantly increased serum concentration of this adipokine." (PMID 27864793, 2017). "We noted significantly higher levels of FABP4 in men with psoriasis compared to women." (PMID 27864793, 2017). "However, in relation to the level of psoriasis activity, FABP4 was decreased, losing its basal significantly higher level in comparison to the controls." (PMID 27864793, 2017). "We can assume that, even though anthralin may be considered an outdated treatment, it may influence lipid metabolism through its impact on FABP4 in patients with psoriasis." (PMID 27864793, 2017). "A further link between FABP4 and psoriasis may be a correlation with tumor necrosis factor-α (TNF-α), which is one of the major cytokines involved in the pathogenesis of this dermatosis." (PMID 27864793, 2017). "Furthermore, the FABP4 protein is also released from adipocytes and macrophages, and it is a proinflammatory signaling protein, with the level of FABP4 protein increasing in the blood of people with the skin inflammatory condition psoriasis." (PMID 34211500, 2021). "Therefore, it must be assumed that serum FABP4 levels in psoriatic patients are dependent not only on the adipose tissue content expressed by BMI, for example, but also on various other modified effectors influencing different inflammatory or immunological stimuli in psoriasis." (PMID 27864793, 2017). "Nevertheless, it underscores the uniqueness of the present study and the need for further study to determine the precise role of FABP4 and FABP3 in the pathogenesis of psoriasis and its comorbidities." (PMID 27864793, 2017). "Thus FABP4 could be a biomarker of psoriasis or a predictor of metabolic disorders and their complications in our patients, particularly those with a mild type of psoriasis." (PMID 27864793, 2017). "Conversely, FABP4 seems to be more closely related to women and age, but it has not been investigated in relation to psoriasis." (PMID 27864793, 2017).
psoriasis (continued). "Although FABP4 is the most commonly known isoform of FABP, no studies have investigated its role in psoriasis." (PMID 27864793, 2017).
thalassemia (4 papers, 2020 to 2026). An inherited blood disorder characterized by a decreased synthesis of one of the polypeptide chains that form hemoglobin. "In logistic regression analysis, FABP4 concentration was identified as a statistically significant risk factor for overall thalassemia-associated cardiometabolic events." (PMID 39028355, 2024). "In conclusion, circulating FABP4 appears to be a potential risk factor for predicting progression to cardiometabolic events in thalassemia-associated adverse metaflammation." (PMID 39028355, 2024). "This study aimed to evaluate the performance of circulating FABP4 as a predictive and diagnostic biomarker for thalassemia-associated cardiometabolic events." (PMID 39028355, 2024). "Circulating FABP4 appears to be a potential risk factor for predicting the progression of cardiometabolic events associated with thalassemia-related adverse metaflammation." (PMID 39028355, 2024). "Circulating FABP4 was identified as a statistically significant risk factor for thalassemia-associated cardiometabolic comorbidities (OR = 84.00, 95%CI:18.6–378.6, p-value < 0.001)." (PMID 39028355, 2024). "Further, FABP4 appears to be a promising risk stratification factor for thalassemia-associated cardiometabolic complications and a potential biomarker for predicting associated risks." (PMID 39028355, 2024). "Further, circulating FABP4 showed a significant diagnostic effect on overall thalassemia-associated cardiometabolic complications (p-value < 0.02)." (PMID 39028355, 2024). "ROC analysis determined that the FABP4 exclusionary cut-off value > 2.30 ng/ml could effectively discriminate between thalassemia-associated adverse metaflammation and controls, while the FABP4 confirmatory cut-off value was > 2.58 ng/ml." (PMID 39028355, 2024). "The diagnostic ability of circulating FABP4 levels for predicting overall thalassemia-associated adverse metaflammation and subsequently cardiometabolic comorbidities was evaluated through ROC analysis, focusing on the area under the curves (AUC) for FABP4." (PMID 39028355, 2024). "Hence, this case-control study of a thalassemia cohort is the first to evaluate the performance of circulating FABP4 as a predictor and diagnostic biomarker for thalassemia-associated cardiometabolic adverse events." (PMID 39028355, 2024). "Furthermore, highly significant differences were observed between the exclusionary FABP4 cut-off value (> 2.30) and thalassemia-associated cardiometabolic adverse events (p-value ≤ 0.05)." (PMID 39028355, 2024). "Understanding the correlation between circulating FABP4 and metaflammation-associated risks in thalassemia could highlight its potential as a therapeutic target for preventing or treating immunometabolic comorbidities in these patients." (PMID 39028355, 2024). "Interestingly, this study suggests that circulating FABP4 could be valuable for clinical monitoring of thalassemia-associated metaflammation and cardiometabolic comorbidities, potentially preventing future complications and optimizing iron-chelation therapy." (PMID 39028355, 2024). "A further prospective, multicentric, larger study comparing thalassemia-associated cardiometabolic abnormalities with the gold standard of iron overload assessment (T2*MRI) is recommended to confirm our findings and validate the diagnostic and prognostic performance of FABP4." (PMID 39028355, 2024). "Comparison with control groups showed significantly higher serum FABP4 levels (p-value < 0.001) among thalassemia patients." (PMID 39028355, 2024). "Overall, this study highlights the importance of early clinical screening in thalassemia patients with FABP4 > 2.3 ng/ml to exclude cardiometabolic risks." (PMID 39028355, 2024). "The thalassemia cohort exhibited a statistically significant higher concentration of FABP4 compared to the control group (p-value < 0.001)." (PMID 39028355, 2024).
thalassemia (continued). "A prospective study with a greater number of subjects and even comparison to healthy subjects is necessary for any further investigation of FABP4 in patients with thalassemia." (PMID 34987673, 2021). "Although this is the first study that sought to explore the correlation between FABP4 and cardiac function in patients with thalassemia major, several limitations need to be considered in the interpretation of the study findings." (PMID 34987673, 2021). "There were correlations between serum FABP4 and cardiac function, as well as serum ferritin in patients with thalassemia major." (PMID 34987673, 2021). "ROC analysis demonstrated that a FABP4 value > 2.30 ng/ml was the exclusionary cut-off point to differentiate and rule out thalassemia-associated cardiometabolic/ adverse metaflammation cases from non-obese controls, with 90% sensitivity and 93.3% specificity." (PMID 39028355, 2024). "Given the chronic inflammation observed in thalassemia, FABP4 levels may reflect the inflammatory burden and predict cardiovascular risk." (PMID 39028355, 2024). "This study is aimed at determining serum FABP4 levels in patients with thalassemia major and whether its concentration correlated with serum ferritin levels, as well as cardiac and liver function." (PMID 34987673, 2021). "Further prospective studies are needed to elucidate whether increased serum FABP4 level is a marker or a potential mechanism for iron-related cardiac involvement in patients with thalassemia major." (PMID 34987673, 2021). "Serum FABP4 correlated with serum ferritin and cardiac function in patients with thalassemia major." (PMID 34987673, 2021). "Consequently, while further studies are essential for a comprehensive exploration of this hypothesis, serum FABP4 may have a potential role in chronic diseases in thalassemia patients." (PMID 41869718, 2026). "Therefore, FABP4 levels could serve as an early marker for subclinical cardiometabolic disturbances in thalassemia patients." (PMID 39028355, 2024). "Moreover, targeting FABP4 for therapeutic benefit may offer promise in reducing the burden of thalassemia-related comorbidities." (PMID 39028355, 2024). "FABP4 may be a potential clinical biomarker for cardiac dysfunction via metabolic and inflammatory pathways due to iron accumulation and toxicity in patients with thalassemia major." (PMID 34987673, 2021). "Therefore, the objectives of this study were to evaluate the serum FABP4 levels in patients with thalassemia major and whether its concentration was affected by iron excess assessed by serum ferritin levels." (PMID 34987673, 2021). "This cohort revealed that circulating FABP4 in thalassemia patients was significantly higher compared to non-obese control individuals." (PMID 39028355, 2024). "Although various adipokines have been implicated in the progression of thalassemia complications, the correlation between FABP4 levels in thalassemia and the development of cardiometabolic comorbidities is not well understood." (PMID 39028355, 2024). "Based on our study, the gender differences in serum FABP4 levels were absent in patients with thalassemia major." (PMID 34987673, 2021). "There was no gender difference regarding serum FABP4 value in patients with thalassemia major." (PMID 34987673, 2021). "Among FABPs, fatty acid-binding protein 4 (FABP4), known as adipocyte FABP, is one of the adipokines that act as a novel biomarker for the metabolic and inflammatory state, and it may be affected in patients with thalassemia major because of the iron excess." (PMID 34987673, 2021). "In this study, although not classified into abnormalities, patients with thalassemia who presented reduced cardiac function based on echocardiography and ECG showed higher levels of serum FABP4." (PMID 34987673, 2021).
viral infection (4 papers, 2021 to 2025). "In addition, we generated a second human adipocyte cell line expressing FABP4-targeting shRNA to achieve long-term suppression of FABP4 and observed a similar reduction in viral infection (Fig. EV3J)." (PMID 39843629, 2025). "We next asked whether the effect of FABP4 on viral infection also applies to other common cold coronavirus infections." (PMID 39843629, 2025). "Following viral infection, developing CD8+ TRM cells in the skin differentially express the fatty-acid-binding proteins 4 and 5 (FABP4 and FABP5), which mediate lipid uptake and intracellular transport." (PMID 33467606, 2021). "Also, cutaneous CD8+ TRM cells lacking Fabp4/Fabp5 in a mouse model were significantly reduced in their ability to resist cutaneous viral infections." (PMID 38596682, 2024).
Abdominal obesity (3 papers, 2011 to 2023). Excessive fat around the stomach and abdomen. "EAT FABP4 mRNA level was reduced only in CAD patients with central obesity as compared with that in the corresponding NCAD individuals." (PMID 34609443, 2021). "In the present study we investigated omentin-1 and FABP4 gene expression in EAT and paired subcutaneous adipose tissue (SAT) samples of patients with CAD and individuals without CAD (NCAD) with or without abdominal obesity." (PMID 34609443, 2021).
acute coronary syndrome (3 papers, 2017 to 2023). Signs and symptoms related to acute ischemia of the myocardium secondary to coronary artery disease. "Further, circulating FABP4 was used as a prognostic biomarker in patients with acute coronary syndrome and stable peripheral artery disease (PAD)." (PMID 32075656, 2020).